NIFK (nucleolar protein interacting with the FHA domain of MKI67)
Synonyms: hNIFK; MKI67IP; NOPP34; Nop15
Tractability: Small molecule: a structure with a bound ligand is known. PROTAC: UniProt records ubiquitination sites on it; ubiquitination databases record sites on it; its protein half-life has been measured.
Gene: Protein-coding gene on chromosome 2 (121,726,945 to 121,736,912, reverse strand). Ensembl gene ENSG00000155438.
Subcellular location: Nucleus, nucleolus; Chromosome
Subcellular location (Human Protein Atlas): Nucleoli; Nucleoli rim; Mitotic chromosome
Gene Ontology:
Molecular function: protein binding; RNA binding; nucleic acid binding
Biological process: protein-containing complex assembly; rRNA metabolic process; rRNA transcription
Cellular component: chromosome; condensed nuclear chromosome; cytoplasm; nucleolus; nucleoplasm
Genetic constraint (gnomAD): Loss-of-function variants: 8 observed, 17.65 expected, observed/expected ratio (o/e) 0.45, 90% interval 0.26 to 0.82. The upper end of that interval is the gene's LOEUF score, 0.82, which puts it in group 3 of 6, group 1 being the genes least tolerant of losing a copy. Missense variants: 189 observed, 189.25 expected, observed/expected ratio (o/e) 1, 90% interval 0.89 to 1.13. Synonymous variants: 71 observed, 69.26 expected, observed/expected ratio (o/e) 1.03, 90% interval 0.85 to 1.25.
Homologues: Orthologues: chimpanzee NIFK (99% identical), macaque NIFK (95% identical), dog NIFK (74% identical), guinea pig NIFK (70% identical), pig NIFK (62% identical), mouse Nifk (59% identical), rat Nifk (58% identical), tropical clawed frog nifk (44% identical), zebrafish nifk (44% identical).
Diseases named in the same sentence as NIFK in open-access papers:
NIFK is named in the same sentence as 15 diseases in open-access papers, as found by Europe PMC text mining. Sharing a sentence is not in itself a finding about the gene and the disease. The quoted sentences say what the papers report.
lung carcinoma (7 papers, 2016 to 2025). "The importance of NIFK in clinical patients motivated us to explore the molecular mechanism underlying NIFK-mediated lung cancer metastasis." (PMID 26984280, 2016). "Our study revealed that the molecular mechanism underlying NIFK-mediated CK1α downregulation in lung cancer is RUNX1-dependent at the transcriptional level." (PMID 26984280, 2016). "In addition, downregulation of CK1α in lung cancer, which induced by NIFK is associated with worse prognosis possibly due to activation of Wnt/β-catenin signaling and stimulation of tumorigenesis." (PMID 29793495, 2018). "Recent studies have shown that NIFK is indispensable for lung cancer development through Ki-67 dependent cell proliferation and CK1α/β-catenin activated metastasis." (PMID 36225931, 2022). "NIFK destabilizes the transcription factor RUNX1 to enhance the metastatic ability of lung cancer cells, thereby stimulating the Wnt/β-catenin signaling pathway." (PMID 35741311, 2022). "On the other hand, the Ki-67-interacting protein Nucleolar protein interacting with the FHA domain of pKi-67 (NIFK) enhanced Ki-67-dependent cell migration and invasion in vitro and metastasis in vivo by reducing CK1α level in lung cancer." (PMID 29793495, 2018). "In our patient cohort, high NIFK IHC expression significantly correlated with poor overall survival in both the Taiwanese (p = 0.018) and Korean (p = 0.041) lung cancer cohorts." (PMID 26984280, 2016). "High NIFK expression correlates with poor prognosis and tumor metastasis in clinical lung cancer patients, suggesting that NIFK is an independent prognostic indicator and a promising therapeutic target." (PMID 26984280, 2016). "We showed the NIFK-induced cell proliferation is dependent on Ki-FHA binding motif indicating the requirement of NIFK-Ki-67 interaction in lung cancer proliferation." (PMID 26984280, 2016). "Lung cancer patients displaying high NIFK expression exhibited poor prognosis and frequent lymph node and distant metastasis." (PMID 26984280, 2016). "The results potentially indicated the requirement of Ki-67 in NIFK-increased cell proliferation and the significance of NIFK and Ki-67 in lung cancer progression." (PMID 26984280, 2016). "In conclusion, NIFK, a Ki-67-interacting protein, is first identified with clinical significance in lung cancer progression." (PMID 26984280, 2016). "Based on the prognostic significance of NIFK and the strong correlation between NIFK and Ki-67 expression in lung cancer, we further investigated the functional role of NIFK in vitro and in vivo." (PMID 26984280, 2016). "In lung cancer cohort, we observed positive correlation of high NIFK/Ki-67 with poor survival at protein level (p = 0.004) and significant expression coefficient (p<0.001)." (PMID 26984280, 2016). "Based on clinicopathological analysis of lung cancer, the patients displaying high NIFK protein expression exhibited more frequent nodal involvement (p = 0.032) and distant metastasis (p = 0.036), as well as a higher pathological stage (p = 0.059)." (PMID 26984280, 2016). "In the lung cancer cohort, the NIFK and RUNX1 or CK1α RNA levels were inversely correlated, whereas the RUNX1 and CK1α RNA expression levels were positively correlated (p<0.001)." (PMID 26984280, 2016). "In 12 lung cancer cell lines, the endogenous NIFK levels were normalized to those of the normal lung cell line Beas2B (Top), and the relative NIFK levels were statistically analyzed (Bottom)." (PMID 26984280, 2016). "A future challenge is to find out whether chemicals that inhibit NIFK could be used in the treatment of lung cancer." (PMID 26984280, 2016).
lung carcinoma (continued). "Our study indicates that NIFK expression promotes cancer metastasis and proliferation leading to poor clinical outcomes; thus, NIFK may represent a prognostic indicator and a promising therapeutic target for lung cancer patients." (PMID 26984280, 2016). "Here we show the clinical significance and metastatic mechanism of NIFK in lung cancer." (PMID 26984280, 2016). "In addition, higher endogenous NIFK levels were detected in H661 and H1299 cells, which were derived from metastatic sites in lung cancer patients (ATCC) and are considered to be invasive." (PMID 26984280, 2016). "Our results demonstrate the prognostic value of NIFK, and suggest that NIFK is required for lung cancer progression via the RUNX1-dependent CK1α repression, which activates TCF4/β-catenin signaling in metastasis and the Ki-67-dependent regulation in cell proliferation." (PMID 26984280, 2016). "Furthermore, we demonstrated that NIFK modulates lung cancer metastasis by regulating TCF4/β-catenin signaling via the alternation of Casein kinase 1α (CK1α) expression." (PMID 26984280, 2016). "NIFK activates TCF4/β-catenin signaling and Ki-67-dependent cell proliferation regulation through RUNX1-dependent CK1α repression and participates in the progression of lung cancer." (PMID 34712323, 2021). "NIFK enhances the metastatic ability of lung cancer cells via the Runx-1-dependent repression of CK1α expression and activates TCF/β–catenin signaling, thereby promoting metastasis in lung cancer." (PMID 26984280, 2016). "Furthermore, the combination of NIFK (MKI67IP) and CK1α (CSNK1A1) may represent a superior prognostic indicator for lung cancer (p = 0.01)." (PMID 26984280, 2016). "Although this negative feedback might serve to regulate lung cancer progression via GSK-3β, CK1α, as the downstream rate-determining enzyme that sequentially phosphorylates β-catenin prior to GSK3β, remains to play a significant role in NIFK regulated β-catenin degradation." (PMID 26984280, 2016).
breast carcinoma (1 paper, 2016). "NIFK was previously implicated as a c-Myc-responsive gene in breast cancer." (PMID 26984280, 2016). "IHC analysis revealed significantly higher expression of NIFK in the samples from our patient cohort than in the paired normal tissue for lung and colorectal cancer but not breast cancer." (PMID 26984280, 2016).
diabetes mellitus (1 paper, 2023). A metabolic disorder characterized by abnormally high blood sugar levels due to diminished production of insulin or insulin resistance/desensitization. "We identified novel targets including CLTC (clathrin heavy chain), TNS2, PLCG1 and NIFK (nucleolar protein interacting with the FHA domain of MKI67) for specific therapy of diabetes mellitus and obesity." (PMID 36837510, 2023).
head and neck squamous cell carcinoma (1 paper, 2024). A squamous cell carcinoma that arises from any of the following anatomic sites: lip and oral cavity, nasal cavity, paranasal sinuses, pharynx, larynx, and salivary glands. "Another study by Li defined seven‐gene NET‐related signature, including ITGA5, NIFK, NUTF2, PDGFα, TNFRSF12, LINC00460 and LINC02454, for head and neck squamous cell carcinoma through the TCGA and ICGC cohorts (p‐value < 0.05)." (PMID 39730971, 2024).
Klebsiella pneumonia (1 paper, 2020). An pneumonia caused by infection with Klebsiella. "The crystal structure of the MoFe protein from Klebsiella pneumonia revealed that the MPP secondary cleavage site within NifD is in close proximity to FeMoco and NifK." (PMID 32868448, 2020).
cancer (8 papers, 2016 to 2025). A tumor composed of atypical neoplastic, often pleomorphic cells that invade other tissues. "Ki-67 interacts with the nucleolar protein NIFK in the forkhead-associated domain to promote cell proliferation and cancer metastasis." (PMID 35741311, 2022). "For example, the PCBP1, SRSF3, and NIFK promotes cancer progression in metastasis or carcinogenesis." (PMID 32219019, 2020). "The significant cancer metastasis-promoting characteristics of NIFK demonstrated by our results provide novel insight into the role of NIFK in cancer." (PMID 26984280, 2016). "Cancer metastasis due to the inhibitory effect of NIFK on the binding of RUNX1 to the CK1α promoter region, as demonstrated by our study, represents a novel tumor progression mechanism that merits further investigation." (PMID 26984280, 2016). "Based on the MetaCore enrichment analysis, Wnt signaling, a previously identified pivotal pathway in regulating cancer metastasis was most strongly affected by NIFK overexpression." (PMID 26984280, 2016). "Surprisingly, our results revealed NIFK significantly promotes cancer migration and invasion in vitro and tumor metastasis in vivo in addition to its ability to regulate cancer proliferation." (PMID 26984280, 2016). "The significant association between NIFK and Ki-67 expression in approximately 20 cancer types based on samples from over 7000 patients in a public database confirmed the importance of NIFK in cancer." (PMID 26984280, 2016). "To identify the cancer types in which NIFK exerts the most significant impact on cancer progression, we examined the prognostic value of NIFK for various cancer types using the PrognoScan database." (PMID 26984280, 2016). "This critical role of the NIFK-Ki-67 interaction in regulating mitosis renders NIFK as a promising target of cancer research." (PMID 26984280, 2016). "In our study, we found that NIFK acts as a critical regulator that prevents CK1α-mediated β-catenin degradation, which in turn leads to cancer metastasis." (PMID 26984280, 2016). "In this study, we aimed to characterize the role of NIFK, an important Ki-67 binding partner, in cancer progression." (PMID 26984280, 2016). "This revealed that, in several different types of cancer, tumors that produced more NIFK were more likely to spread to other parts of the body than tumors that produced smaller amounts of NIFK." (PMID 26984280, 2016). "In this study, we demonstrate that NIFK promotes cancer progression by regulating cancer metastasis and proliferation." (PMID 26984280, 2016). "The Nop15 ortholog from humans, NIFK, has a crucial function in cell cycle progression and may even promote cancer progression, thus indicating an important role of Nop15-type proteins in development." (PMID 37316549, 2023). "NIFK downregulation in H661 and H1299 cells decreased the cancer proliferation at 96 hr in vitro." (PMID 26984280, 2016). "Nevertheless, how NIFK functions in human cancers is largely unknown." (PMID 36225931, 2022). "Second, further analysis has identified seven NET-related genes, including NIFK, LINC00460, NUTF2, and LINC02454, some of which are potentially predictive biomarkers for human cancers." (PMID 36225931, 2022). "These include POLK, NIFK, SRGN, CAMP, CD109, and PLAC1 that are upregulated in several cancers resulting in metastasis and poor prognosis." (PMID 33110154, 2020). "A significantly positive correlation between MKI67IP (NIFK) and MKI67 (Ki-67) was observed in almost all cancer types." (PMID 26984280, 2016). "However, the function of NIFK in human cancer development is not clear." (PMID 36225931, 2022). "However, to date, studies focused on the importance of NIFK in cancer are lacking, and no clear evidence has emerged to elucidate whether and how NIFK regulates cancer progression." (PMID 26984280, 2016). "However, our results imply that Ki-67 may not affect cancer metastasis via its interaction with NIFK." (PMID 26984280, 2016).
tumor (7 papers, 2015 to 2023). "Then, we, for the first time, found that NIFK was significantly upregulated in HNSCC patient samples, and its levels were significantly linked to tumor malignancy and immune status." (PMID 36225931, 2022). "After reviewing the literature, we found that four upregulated genes comprising of TUBA1C, ABCE1, UBE2N, and NIFK had been reported to function in tumor growth, proliferation, migration, metastasis, and prognosis." (PMID 31867042, 2019). "In addition, the GSVA heatmap showed several NIFK associated pathways, such as GO immune-related functions and KEGG tumor-related pathways." (PMID 36225931, 2022). "A total of 12 upregulated and one downregulated genes were found to overlap with prognostic and fitness genes, in which four upregulated genes (TUBA1C, ABCE1, UBE2N, and NIFK) had been reported to play roles in tumor growth, cell cycle, migration, metastasis, and prognosis." (PMID 31867042, 2019). "Next, we performed animal experiments to examine whether CK1α is involved in NIFK-regulated tumor metastasis." (PMID 26984280, 2016). "We further investigated whether NIFK-induced tumor metastasis is mediated by the CK1α." (PMID 26984280, 2016). "Additionally, in vivo animal model experiments were performed to examine whether NIFK promotes tumor metastasis." (PMID 26984280, 2016). "We also found a significant reduction in the levels of tumor promoter GPs at the end of 4th week during 4-week intermittent fasting (POLK, CD109, CAMP, NIFK, SRGN), and 1 week after 4-week intermittent fasting (CAMP, PLAC1) compared with the levels before 4-week intermittent fasting." (PMID 33110154, 2020).
NIFK also shares sentences with these, for which no sentence is quoted: atherosclerosis (1 paper); blood cancer (1); colitis (1); colorectal cancer (1); glioblastoma (1); melanoma (1); Obesity (1); ovarian carcinoma (1).